AXL (AXL receptor tyrosine kinase)
Diseases named in the same sentence as AXL in open-access papers (continued):
Sharing a sentence is not in itself a finding about the gene and the disease.
colon carcinoma (continued). "In this study, we analyzed the mRNA expression of YAP and TAZ, and two of its downstream target genes, AXL and CTGF, in two independent colon cancer patient cohorts comprising 522 patients." (PMID 23372686, 2013). "The expression levels of TAZ and YAP, and their downstream transcriptional targets, AXL and CTGF, were extracted from two independent colon cancer patient datasets available in the Gene Expression Omnibus database, totaling 522 patients." (PMID 23372686, 2013). "Our results, therefore, strongly suggest that TAZ, AXL and CTGF can be used in combination for prognostification in colon cancer patients." (PMID 23372686, 2013). "Neither the age nor sex of the patients was factor that determined the number of TAZ, AXL and CTGF that overexpressed in either colon cancer patient cohort." (PMID 23372686, 2013). "Here, we described an assay to detect AXL expression on the surface of CTCs from patients with mBC using the CellSearch® system, the only FDA‐approved method to detect CTCs in metastatic breast, prostate, and colon cancer." (PMID 38132919, 2023). "Moreover, AXL was shown as a major regulator of migration, invasion, and epithelial–mesenchymal transition (EMT) in colon cancer cells." (PMID 36409270, 2023). "To further investigate whether TAM RTKs can induce cell proliferation and apoptosis in colon cancer cells, we downregulated the expression of TAM RTKs using specific siRNAs targeting TYRO3, AXL and MER." (PMID 34721022, 2021). "It has also been reported that downregulation of AXL in colon cancer cells is involved in metastasis rather than in cell proliferation." (PMID 34721022, 2021). "To examine the relevance of YAP and TAZ in the control of cellular quiescence and growth of disseminated colon tumor cells, we have compared expression of YAP/ TAZ and Ki-67, Cyr61, AXL, and CTGF using RT-qPCR in liver metastases resected from 70 colon cancer patients." (PMID 27527859, 2016). "Expression of TAZ, AXL and CTGF all correlated with colon cancer patient survival." (PMID 23372686, 2013). "With respect to whether GALNT2 can regulate ligand‐dependent activation of AXL, unfortunately, we could not detect sufficient amount of phospho‐AXL in colon cancer cells to draw a conclusion." (PMID 36409270, 2023). "In previous reports, AXL in colon cancer was not correlated with patient survival." (PMID 34721022, 2021). "Furthermore, AXL was expressed in only two colon cancer cell lines, SW480 and SW620, and was not expressed in DLD1, HCT15, LoVo, and HT29 cells." (PMID 34721022, 2021). "Recently, AXL has been demonstrated as a key regulator of inherent and chemotherapy-induced invasion in invasive or migratory CRC cell subpopulations with an EMT-like phenotype and increased AXL levels predict a poor clinical outcome in early stage colon cancer." (PMID 25337673, 2014). "Interestingly, the upregulation of AXL and CTGF, which reflects the increased transcriptional activity of TAZ-TEAD complexes, can be used in combination with TAZ mRNA expression, for better prognostification in these two independent colon cancer patient datasets." (PMID 23372686, 2013).
sarcoma (20 papers, 2015 to 2025). A usually aggressive malignant neoplasm of the soft tissue or bone. "The single nucleotide variant (SNV) status of the AXL gene (NM_021913) was reviewed in each of the 19,879 unique sarcomas in our own database." (PMID 38369783, 2024). "The sole AXL mutations for which there were multiple cases of the same sarcoma subtype were W451C and W450C." (PMID 38369783, 2024). "The recurrence of the 2 AXL point mutations in our sarcoma data set (n = 10/19,879) prompted us to interrogate an additional database—namely, the sarcoma genomic data set of the TCGA Network." (PMID 38369783, 2024). "Recurrent amplification-dependent overexpression of AXL, which encodes a receptor tyrosine kinase, was identified in two sarcoma samples." (PMID 28377632, 2017). "Among them, AXL, which encodes a receptor tyrosine kinase, was recurrently overexpressed and amplified in sarcomas." (PMID 28377632, 2017). "Notably, the only genomic alterations recurrent in a specific sarcoma subtype were AXL W451C (n = 8) and AXL W450C (n = 2) mutations." (PMID 38369783, 2024). "Moreover, several sarcoma-associated gene mutations were found, including AR mutation (p.G473del, 11.11%), AXL mutation (p.T45P, 8.11%), and ETV5 mutation (p.F11Y, 33.33%)." (PMID 36153506, 2022). "The sarcoma cohort was included based on the known intrinsically high expression of AXL in these tumors as well as preclinical studies that showed EnaV was able to elicit antitumor activity in patient-derived xenograft models of soft-tissue sarcoma." (PMID 41166388, 2025). "We further report sarcomas of diverse histologic subtypes with AXL gene amplifications, with the highest frequency of amplification identified in MFS cases without the W451C mutation." (PMID 38369783, 2024). "In the current study, we sought to assess a possible role for AXL abnormalities in MFS through a search for AXL genomic alterations across large data sets of sarcomas." (PMID 38369783, 2024). "Another study showed abundant tyrosine phosphorylation and expression of AXL in cell lines of ten sarcomas, including RMS samples." (PMID 36918772, 2023). "Here, we propose an innovative immunotherapeutic strategy based on the targeting of AXL, using a first-in-class PronectinTM-based Bispecific T-Cell Engager (pAXL×CD3ε) for the treatment of sarcomas." (PMID 36980534, 2023). "AXL expression was first analyzed by flow cytometry, qRT-PCR, and Western blot on a panel of sarcoma cell lines." (PMID 36980534, 2023). "On these premises, we focused on AXL as an immunotherapeutic target to be exploited in sarcoma treatment by BTCE-based strategy." (PMID 36980534, 2023). "Based on this rationale, we investigated the in vitro and in vivo activity of a first-in-class pBTCE targeting AXL (pAXL×CD3ε) as a potential immunotherapeutic agent for the treatment of sarcomas." (PMID 36980534, 2023). "Recently, different strategies based on mAbs and CAR-T cells showed encouraging results against AXL-expressing sarcomas and some of them are currently under clinical investigation." (PMID 36980534, 2023). "Previous studies, using mAbs against AXL, have reported activity and manageable toxicity in sarcoma patients, suggesting its targeting potential also in the clinical setting." (PMID 36980534, 2023). "Consistently, here we demonstrated that pAXL×CD3ε indeed redirects T cells toward AXL-expressing sarcoma cells, leading to a dose-dependent T-cell activation, with a consequent release of inflammatory cytokines and cytolytic molecules." (PMID 36980534, 2023). "Further Western blot analyses were performed to investigate the expression of AXL protein in sarcoma cells, reporting a clear difference in the band intensity between various cell lines." (PMID 36980534, 2023).
sarcoma (continued). "Our results demonstrate that pAXL×CD3ε redirects T cells toward AXL-expressing sarcoma cell lines, leading a dose-dependent and T cell-mediated cytotoxicity in vitro." (PMID 36980534, 2023). "Our data demonstrate that AXL is highly expressed in sarcoma cells, therefore representing a potential mean for selective targeting." (PMID 36980534, 2023). "This study provides a preclinical rationale for the evaluation of AXL-targeting ADCs in the treatment of AXL-expressing sarcomas." (PMID 35886842, 2022). "The present study provides the preclinical rationale for further clinical investigation of AXL-targeted therapies in patients with AXL-expressing sarcomas." (PMID 35886842, 2022). "According to publicly available gene expression data from the Cancer Genome Atlas (TCGA) regarding treatment-naïve tumors, sarcomas in general have the highest intrinsic AXL expression among all cancer types." (PMID 35886842, 2022). "We believe this approach has advantages over the use of selective AXL signaling inhibitors in sarcomas that are displaying complex karyotypes (>80% of STS) and are potentially driven by multiple oncogenic pathways." (PMID 35886842, 2022). "Based on this, we evaluated INCB081776 for antitumor activity in sarcoma PDX models that expressed AXL and/or MERTK." (PMID 33425754, 2020). "Dysregulation of the receptor tyrosine kinase AXL is known to promote cancer cell growth and survival in many sarcomas, including the rare subtype, malignant peripheral nerve sheath tumors (MPNST)." (PMID 33283192, 2020). "Recurrent amplification-dependent overexpression of AXL was observed only in two sarcomas (myxofibrosarcoma and leiomyosarcoma)." (PMID 28377632, 2017). "Including this case, AXL amplification-dependent overexpression was observed in three of a total of 19 sarcoma samples (16%)." (PMID 28377632, 2017). "AXL is a well-characterized, protumorigenic receptor tyrosine kinase that is highly expressed and activated in numerous human carcinomas and sarcomas, including aggressive subtypes of liposarcoma." (PMID 26573603, 2015). "Tumoral AXL expression at baseline (from tumor biopsies collected following disease progression on the last prior therapy) was generally low (≤15% median AXL+ tumor cells) in all cohorts except for sarcoma (68.8% median AXL+ tumor cells), a tumor type with known high intrinsic AXL expression." (PMID 41166388, 2025). "A single AXL W451C-mutant sarcoma was identified (one of 206 sarcomas)." (PMID 38369783, 2024). "Expression of AXL messenger RNA is elevated in a variety of sarcoma types, with the highest levels reported in MFS, but the pathogenic significance of this finding remains unknown." (PMID 38369783, 2024). "Here, we assessed that AXL is highly expressed among a variety of sarcomas, confirming previous data performed on primary sarcoma samples and representing a promising target for the development of innovative immunotherapeutic approaches, especially in chemo-refractory disease." (PMID 36980534, 2023). "Through qRT-PCR analysis, we assessed the AXL mRNA expression in sarcoma cells." (PMID 36980534, 2023). "At this moment, at least four ADCs are under clinical investigation in sarcoma addressing targets such as AXL, neural cell adhesion molecule (NCAM), receptor tyrosine kinase-like orphan receptor (ROR), and many others are being evaluated in preclinical studies." (PMID 35886842, 2022). "Their study highlighted sarcoma where AXL was reported as drug target." (PMID 35580047, 2022). "Since the relationship between levels of amplification and overexpression is currently unclear, from a clinical perspective, it will be of interest to determine the prognostic significance of AXL amplification-dependent overexpression in sarcoma tumors in the future." (PMID 28377632, 2017). "No AXL W451C mutations were identified in any of the 443,667 non-sarcoma tumors." (PMID 38369783, 2024). "The AXL W451C mutation was not identified in any non-sarcoma malignancy." (PMID 38369783, 2024).
sarcoma (continued). "In the BA3011 study (NCT03425279, AXL-targeted antibody-drug conjugate (ADC), mecbotamab vedotin, is tested alone and with nivolumab in patients with advanced sarcomas, including MFS." (PMID 41562047, 2025). "AXL, a TAM family tyrosine kinase receptor, recently emerged as an interesting target for several type of sarcomas." (PMID 36980534, 2023). "We developed an innovative immunotherapeutic agent, a first-in-class PronectinTM-based Bispecific T-Cell Engager (pAXL×CD3ε), for the targeting of AXL, a TAM family tyrosine kinase receptor highly expressed in sarcomas." (PMID 36980534, 2023). "We evaluated EnaV, an AXL-specific ADC, in sarcoma PDX models and explored the potential of AXL expression as a predictive biomarker to support further development of AXL-targeted therapies in this setting." (PMID 35886842, 2022). "Moreover, AXL gene amplifications and messenger RNA overexpression are far more frequent in MFS than in other sarcoma subtypes." (PMID 38369783, 2024). "Available data on RNA expression showed that the AXL mRNA level, in this case, was not conspicuously elevated, falling within the second quartile of sarcoma overall (6.48 transcripts/million; Q2 for sarcomas spans 5.8 to 6.7)." (PMID 38369783, 2024). "In particular, 2.5% of MFS showed tetraploid or greater AXL amplification compared with only 0.5% of non-MFS sarcoma (8/315 vs 96/19564, P < 0.0001, χ2 test with Yates correction)." (PMID 38369783, 2024). "The immunogenicity and antitumor efficacy of BA3011, a conditionally active biologic (CAB) AXL-targeted antibody drug conjugate (CAB-AXL-ADC), is being investigated in a phase I/II study in different sarcoma subtypes, in monotherapy or combined with a PD-1 inhibitor (NCT03425279)." (PMID 36980534, 2023). "Finally, a trial has been completed on different tumor types, including sarcoma, to investigate the safety and efficacy of Enapotamab Vedotin (HuMax-AXL-ADC), an AXL-specific antibody drug conjugate (NCT02988817)." (PMID 36980534, 2023). "AXL-CAR-T cells have entered clinical trials (phase I for lung and solid tumors NCT03198052; NCT04842812, phase I/II refractory stage IV RCC NCT03393936, and sarcomas NCT05128786)." (PMID 35572601, 2022). "Besides playing roles in the regulation of immunity, AXL and MERTK provide growth and survival signals to the tumor cells directly.Sarcomas are a mesenchymal tumor type where elevated AXL and MERTK expression has been observed." (PMID 33425754, 2020). "Mecbotamab vedotin (BA3011) is a conditionally active anti-AXL and MMAE ADC currently under clinical investigation in a phase 1/2 study of mecbotamab vedotin alone or in combination with nivolumab in adult and adolescent patients with advanced refractory sarcoma (NCT03425279)." (PMID 41166388, 2025). "To assess a role for AXL abnormalities in MFS, we undertook a search for AXL genomic alterations in a comprehensive genomic profiling database of 463,546 unique tumors (including 19,879 sarcomas, of which 315 were MFS) interrogated by targeted next-generation DNA and/or RNA sequencing." (PMID 38369783, 2024). "According to our results, AXL expression is not correlated to specific sarcoma sub-types." (PMID 36980534, 2023). "Whereas the low levels of AXL expression in some of the cohorts may explain the lack of clinically meaningful activity by EnaV, no objective responses were observed in patients in the sarcoma cohort despite having the highest median percentage of AXL-positive tumor cells." (PMID 41166388, 2025).
gastric cancer (19 papers, 2016 to 2026). A primary or metastatic malignant neoplasm involving the stomach. "We performed this study to evaluate the antitumor impact of LY2801653, a dual MET and AXL inhibitor on gastric cancer and to elucidate the underlying mechanisms." (PMID 34766112, 2020). "In addition, increased AXL phosphorylation in gastric cancer tissues is associated with decreased overall survival." (PMID 40485724, 2025). "High expression of phosphorylated AXL was associated with poor survival in gastric cancer patients." (PMID 38562556, 2024). "Silencing or inhibition of AXL reverted this phenotype and decreased the number of peritoneal nodules in a gastric cancer mouse model." (PMID 38562556, 2024). "Previous studies have underscored the critical role of the GAS6/AXL signaling axis in driving the aggressive behavior of gastric carcinoma cells, particularly through interactions with cancer-associated fibroblasts (CAFs)." (PMID 39597836, 2024). "High mRNA and protein expression of Gas6 and AXL has been reported in human gastric cancer cell lines and tissues." (PMID 37469409, 2023). "For instance, high levels of Gas6 and AXL mRNA and proteins were revealed in human gastric cancer cell lines and tissue samples, and Gas6 expression was significantly correlated with metastases to lymph nodes." (PMID 37469409, 2023). "Obviously, YES1, MET, and AXL activation in HER2-driven gastric cancer cells is a new mechanism for producing resistance, while the use of the corresponding activation inhibitor is a reliable method." (PMID 34976824, 2021). "Afatinib induces the activation of MET and AXL in HER2-driven resistant gastric cancer cell lines, which can be inhibited by cabozantinib so as to reduce resisitance." (PMID 34976824, 2021). "In our study, LY2801653 demonstrated potent antitumor effects on MET and AXL‐dependent MKN45 gastric cancer cells as well as MKN45‐derived xenograft models by killing tumor cells directly." (PMID 34766112, 2020). "We evaluated the expression of MET and AXL in a panel of seven gastric cancer cell lines by quantitative real‐time PCR (qPCR) and Western blot analyses." (PMID 34766112, 2020). "The activity of LY2801653 against moderate MET and AXL expression gastric cancer xenograft model, SNU719, was also explored." (PMID 34766112, 2020). "The present findings established that both MET and AXL were independent predictors of gastric cancer prognosis." (PMID 34766112, 2020). "In conclusion, our study provides evidence for MET and AXL as prognostic biomarkers and potential therapeutic targets in gastric cancer." (PMID 34766112, 2020). "In this study, we investigated the antitumor effects of LY2801653 (merestinib), an oral ATP‐competitive, dual MET, and AXL tyrosine kinase inhibitor, on gastric cancer." (PMID 34766112, 2020). "The dual MET/AXL inhibitor LY2801653 represents a promising therapeutic strategy for the treatment of patients with gastric carcinoma." (PMID 34766112, 2020). "In this work, we characterized the changes of site-specific glycosylation in secretory AXL during the acquisition of MDR in stomach cancer for the first time." (PMID 27015365, 2016). "In addition, studies have shown that CAF-derived growth arrest-specific 6(GAS6) in gastric cancer can promote the proliferation and migration of gastric cancer cells by phosphorylating receptor tyrosine kinase (AXL)." (PMID 40485724, 2025). "Blockage of MET and AXL signaling might contribute to the antitumor effects in gastric cancer by inducing growth arrest and apoptosis in gastric cancer cell lines and suppressing cell growth in immunocompromised mice with no obvious toxicities." (PMID 34766112, 2020). "Meanwhile, AXL could also serve as a survival predictor with detrimental OS in gastric cancer patients." (PMID 34766112, 2020). "However, few reports are available regarding the combinatorial targeting of MET and AXL in gastric cancer." (PMID 34766112, 2020).